NMT2 (N-myristoyltransferase 2)
Description:
Adds a myristoyl group to the N-terminal glycine residue of certain cellular and viral proteins. Also able to mediate N-terminal lysine myristoylation of proteins: catalyzes myristoylation of ARF6 on both 'Gly-2' and 'Lys-3'. Lysine myristoylation is required to maintain ARF6 on membranes during the GTPase cycle.
Tractability: Small molecule: a structure with a bound ligand is known; a high-quality ligand is known. Antibody: UniProt places it where antibodies can reach, with high confidence; its Gene Ontology location is reachable by antibodies, with high confidence; the Human Protein Atlas places it where antibodies can reach. PROTAC: ubiquitination databases record sites on it; its protein half-life has been measured; a small molecule that binds it is known.
Target class: Enzyme; Transferase
Chemical probes: DDD85646 (high quality), IMP-1088 (high quality)
Gene: Protein-coding gene on chromosome 10 (15,102,584 to 15,168,719, reverse strand). Ensembl gene ENSG00000152465.
Subcellular location: Cytoplasm; Membrane
Subcellular location (Human Protein Atlas): Cytosol; Golgi apparatus; Plasma membrane
Pathways (Reactome):
Disease: Membrane binding and targetting of GAG proteins
Metabolism: eNOS activation
Sensory Perception: Inactivation, recovery and regulation of the phototransduction cascade
Gene Ontology:
Molecular function: glycylpeptide N-tetradecanoyltransferase activity; peptidyl-lysine N6-myristoyltransferase activity; protein binding; CoA-dependent peptidyl-lysine N6-myristoyltransferase activity
Biological process: N-terminal peptidyl-glycine N-myristoylation; intracellular transport of virus; protein localization to membrane; regulation of opsin-mediated signaling pathway
Cellular component: cytoplasm; cytosol; Golgi apparatus; membrane; plasma membrane; host cell
Genetic constraint (gnomAD): Loss-of-function variants: 27 observed, 50.54 expected, observed/expected ratio (o/e) 0.53, 90% interval 0.39 to 0.74. The upper end of that interval is the gene's LOEUF score, 0.74, which puts it in group 3 of 6, group 1 being the genes least tolerant of losing a copy. Missense variants: 421 observed, 539.77 expected, observed/expected ratio (o/e) 0.78, 90% interval 0.72 to 0.85. Synonymous variants: 201 observed, 209.45 expected, observed/expected ratio (o/e) 0.96, 90% interval 0.86 to 1.08.
Homologues: Orthologues: chimpanzee NMT2 (100% identical), mouse Nmt2 (96% identical), rat Nmt2 (96% identical), guinea pig NMT2 (95% identical), pig NMT2 (95% identical), dog NMT2 (94% identical), tropical clawed frog nmt2 (88% identical), zebrafish nmt2 (86% identical), macaque NMT2 (84% identical), rabbit NMT2 (81% identical), Drosophila melanogaster Nmt (55% identical), Caenorhabditis elegans nmt-1 (48% identical). Paralogues in human: NMT1 (75% identical).